ANXA2 (annexin A2)
Diseases named in the same sentence as ANXA2 in open-access papers (continued):
Sharing a sentence is not in itself a finding about the gene and the disease.
cancer (continued). "Mechanistically, LINC01614 directly interacts with ANXA2 and p65 to facilitate the activation of NF-κB, which leads to the upregulation of the glutamine transporters SLC38A2 and SLC7A5 and eventually enhances the glutamine influx of cancer cells." (PMID 36209111, 2022). "The expression of serum exo-AnxA2 levels was significantly elevated in TNBC (n = 68; 109.1 ± 2.905 ng/mL; P < 0.0001) in comparison to ER+ (n = 50; 57.35 ± 1.545 ng/mL), HER2+ (n = 59; 78.25 ± 1.146 ng/mL), and non-cancer females (n = 68; 34.21 ± 2.238 ng/mL)." (PMID 31992335, 2020). "The same study demonstrated that LF-derived cathepsin B (CTSB) induced SCD1 overexpression in B16F10 cells via annexin A2 (ANXA2) and the PI3K/Akt/mammalian/mechanistic target of rapamycin (mTOR) pathway, which is critical for cellular metabolism and cancer progression." (PMID 31284458, 2019). "The roles of LAMC2, ANXA2, ADAM9, and APLP2 in cancer biology have been documented." (PMID 30700038, 2019). "Our approach covers a broad spectrum of cancer biology, of which LAMC2, ANXA2, ADAM9, and APLP2 are the most important features of the tested diagnostic model, and their implementation in clinical settings could be further examined." (PMID 30700038, 2019). "The interaction between annexin A2, S100A10, and t-PA mediates the conversion of plasminogen to plasmin, which facilitates the ECM degradation, MMP activation, and angiogenesis, leading to increased cancer cell migration, invasion, and metastasis." (PMID 30572596, 2018). "In addition to cancer progression, ANX family proteins (ANXA1 and ANXA2) suppress the efficacy of both chemotherapy and radiotherapy." (PMID 29598816, 2018). "Notably, Annexin A2 interacts with EGFR at the cell surface and has an important role in cancer cell proliferation and migration by modulating EGFR functions." (PMID 28886730, 2017). "Validation studies revealed cyclophilin A, annexin A2, and aldolase A mRNA and protein expression levels were significantly higher in cancer regions than in non-cancer regions." (PMID 27468721, 2016). "We also found that Annexin A2 suppressed DOCK8 expression, indicating that DOCK8 may be involved in Annexin A2-regulated cancer migration and progression." (PMID 26716413, 2016). "Annexin 2A (also called annexin II, ANXA2, calpactin I or lipocortin II), is a calcium-binding cytoskeletal protein expressed on the surface of endothelial cells, macrophages, mononuclear cells and various types of cancer cells." (PMID 27429043, 2016). "Thus, the detailed mechanism through which Anxa2 promotes EMT and cancer progression must be identified." (PMID 26307676, 2015). "The systemic administration of annexin A2 antibody inhibits tumour growth and metastasis in murine cancer models in vivo without detectable toxicity." (PMID 25878399, 2015). "In HeLa cells, more extensive co-localisation of AnxA2 and EEA1 was observed, possibly due to the increased Tyr23 phosphorylation of AnxA2, which is a typical feature of cancer cells such as HeLa and Tyr23 phosphorylation of AnxA2 is essential for its proper endosomal association." (PMID 23555942, 2013). "Furthermore, we found that exosomal AnxA2 is functionally active (MCF-10CA1A exosomal AnxA2 having more angiogenic potential than MCF-10A), indicating a possible role of exosomal AnxA2 in cancer progression." (PMID 26082317, 2013). "A significant correlation was identified between the serum and cancer tissue ANXA2 levels (r=0.364, P=0.017), but not between the serum and the non-cancer tissues (r=0.243, P=0.160) in the HCC patients." (PMID 23946789, 2013). "Collectively, the increase in active Src (pSrc Y416), EGFR and AnxA2 upon Herceptin therapy and decrease in phosphorylation of Src and EGFR suggests that the cancer cells reprogram themselves by upregulation of a group of proteins which work together to overcome any stress such as Herceptin therapy." (PMID 22957061, 2012).
cancer (continued). "We noted that depletion of ANXA2 did not seem to significantly affect the basal levels of ROS in normal (TIME) or cancer cells (MCF7 and LLC)." (PMID 22185818, 2011). "In this study, we show that although ANXA2-null mice do not have an overt phenotype under non-pathological conditions, ANXA2 plays an important role during disease, namely supporting cancer progression by acting as a redox regulatory protein." (PMID 22185818, 2011). "Interestingly, an abundance of AHNAK and annexin A2 were found in extracellular vesicles released by mammary cancer cells towards non-cancer mammary fibroblasts, indicating a role for AHNAK in vesicular communication promoting cancer progression." (PMID 35158796, 2022). "In addition, a clear interaction between ANXA2 and ANXA1 has been observed, which suggested that these two proteins might work together to promote the rapid proliferation of cancer cells." (PMID 32351780, 2020). "Nevertheless, a cancer preventive effect of Lm-ANXA2 cannot be ruled out." (PMID 31113479, 2019). "As G-Rg5 and G-Rk1 failed to interact with Annexin A2-K302A, G-Rg5 or G-Rk1 could not inactivate the other pathway triggered NF-κB activation, presenting little anti-cancer activity in Annexin A2-K302A over-expressed HepG2 cells." (PMID 29508276, 2018). "Not only because many studies indicated that NF-κB activation is involved in cancer drug-resistance, but also studies have indicated that other ANX family member (ANXA4) could interact with the NF-κB subunit, and ANXA2 has a similar conserved structure domain with ANXA4." (PMID 28814318, 2017). "We therefore propose that ANXA2 may be used for target therapy on NPC and perhaps other cancers." (PMID 25402728, 2015). "Interestingly, ANXA2 is co-expressed with YAP in activated stellate cells and in cancer cells." (PMID 26567630, 2015). "Thus, ourdata, linking ANXA2 and EMT in PDA, provide a new pathway that may regulate the EMTprocess that occurs in cancer invasion and metastases." (PMID 21572519, 2011). "Interestingly, when we depleted PRDX2 in cancer cells we did not observe up-regulation of ANXA2." (PMID 30959964, 2019). "Therefore, ANXA2 may not be produced and released by cancer only and it is therefore not a valid biomarker." (PMID 23946789, 2013). "Examples such as ANXA2 and PRDX4 show significant enrichment in the chromatin accessibility of the cancer-specific enhancers compared to the non-malignant cell types, resulting in marked increases in gene expression." (PMID 37685859, 2023). "The most significant gene that is up-regulated in cancer on our list (but not in the original paper) is tag, "CTTCCAGCTA", which represents the annexin A2 gene." (PMID 15987513, 2005). "In contrast, depletion of PRDX2 by shRNA did not lead to up-regulation of ANXA2 in either MDA-MB-231, MCF7 or HCT-116 cancer cells.To investigate if the up-regulation of PRDX2 in HT1080 ANXA2 KO cells was regulated by ROS, we treated these cells with the antioxidant N-acetyl cysteine (NAC)." (PMID 30959964, 2019). "ANXA2 is rarely detected in either normal or chronic hepatic tissues but is overexpressed transcriptionally and translationally in tumorous and nontumorous regions of HCC (primarily localized in cancer cells), especially in poorly differentiated HCC (P < 0.01)." (PMID 24591759, 2014).
infection (64 papers, 2010 to 2026). The state of being infected such as from the introduction of a foreign agent such as serum, vaccine, antigenic substance or organism. "At 12 h and 24 h post-infection, both E. coli and P. aeruginosa resulted in elevated ROS levels and IL-17A production under AnxA2 deficiency." (PMID 27389701, 2016). "It was previously demonstrated that SLPI inhibits the infection of HIV-1 through extracellular annexin A2, and HSV causes a sustained down-regulation of SLPI." (PMID 22927980, 2012). "In conclusion, the infection caused by E. tenella influences ANXA2 expression." (PMID 40777830, 2025). "Moreover, multiple Annexin A2 effects play a vital role in the transport of Cryptococcus neoformans, demonstrating Annexin A2’s distinctive role in the replication and infection of various viruses, pathogenic bacteria, mycoplasmas, parasites, and fungi." (PMID 37482693, 2023). "Furthermore, Annexin A2 can facilitate infections caused by Pseudomonas aeruginosa, Salmonella typhimurium, Escherichia coli, and other pathogens by mediating bacterial adhesion and invasion." (PMID 37482693, 2023). "However, silencing AnxA2 causes a decrease in the expression of viral proteins Hemagglutinin (HA) and Matrix (M), which are required for viral attachment and infection." (PMID 34681689, 2021). "Annexin A2 fulfills a number of protective roles during pathogenic infection." (PMID 32575495, 2020). "Moreover, Anxa2-/--infected mice were significantly more susceptible to infection than wild-type mice, indicating that AnxA2 helps this pathogen evade the NLRC4 inflammasome-based host defense system." (PMID 32575495, 2020). "Here we report that ANXA2-knockout (KO) mice are more susceptible to CMHs in response to rickettsia and Ebola virus infections, suggesting an essential role of ANXA2 in protecting vascular integrity during these intracellular pathogen infections." (PMID 32687500, 2020). "This might indicate that ANXA2 polymorphisms play a less important role in infection efficiency and host susceptibility than SCARB2 and PSGL-1 polymorphisms." (PMID 30395634, 2018). "Other viruses associated with annexin A2 also utilize similar molecules during infection." (PMID 22927980, 2012). "This study established an in vitro primary culture model of chicken embryonic cecal epithelial cells, employed RNA interference (RNAi) to knockdown ANXA2, and assessed apoptosis-related parameters following infection with E. tenella sporozoites." (PMID 40777830, 2025). "Following sporozoite inoculation for 4 to 96 h, the infection rate in the siRNA ANXA2 + E. tenella group was significantly lower than that in both the E. tenella and NC siRNA + E. tenella groups (P < 0.01)." (PMID 40777830, 2025). "Then, to confirm the role SCARB2 and ANXA2 play in EV-A71 infection, a blocking experiment was carried out in tree shrew brain MVECs." (PMID 40642060, 2025). "Previous reports have demonstrated that ANXA2 plays unique roles in the infection mechanisms of various pathogens." (PMID 40777830, 2025). "Our results revealed that knocking down the expression of ANXA2 reduces the infection rate of E. tenella." (PMID 40777830, 2025). "The result indicates that knocking down the ANXA2 expression can reduce the infection rate of E. tenella." (PMID 40777830, 2025). "ANXA2 is involved in infection by various bacteria, such as Rickettsia, Escherichia coli, and Salmonella." (PMID 39057791, 2024). "Using stable isotope labeling of amino acids in cell culture (SILAC) in an infection-based assay of epithelial cells, the host protein annexin A2 (AnxA2) was identified as a candidate interactor of both SopD2 and SPI-2 T3SS effector PipB2." (PMID 38673776, 2024). "In this context, we show that As can reduce the expression of S. aureus clumping factor (ClfB) and block its interaction with the host Annexin A2 (AnxA2), resulting in decreased bacterial adherence in infection of MAC-T cells." (PMID 38414081, 2024).
infection (continued). "To achieve this, we have pre-treated MAC-T cells with AnxA2 antibody for 3 h prior infection with S. aureus and the inclusion of As." (PMID 38414081, 2024). "During the early stages of infection, ANXA2, as a cell surface receptor, facilitates the adhesion and internalization of bacteria and viruses, promoting their replication, assembly, and release, which is detrimental to the host organism." (PMID 39057791, 2024). "This suggests that Mycoplasma bovis can use ANXA2 to promote its infection and influence the cow’s inflammatory response." (PMID 39057791, 2024). "Analysis of plasma samples collected from AC70 hACE2 Tg mice showed markedly elevated levels of IgG anti-ANXA2 antibodies, compared to those collected prior to infection." (PMID 38913740, 2024). "This review provides an overview of the research progress on how ANXA2 regulates pathogen infections." (PMID 39057791, 2024). "Overall, this paper demonstrates the importance of ANXA2 in pathogen infections by describing the signaling pathways in which ANXA2 is involved and its role in various pathogen infections." (PMID 39057791, 2024). "Previously, it has been shown that AnxA2 can interact with a bacterial receptor, mediating the adhesion to the host cells and ultimately promoting host infection." (PMID 38414081, 2024). "In our study we show that As can inhibit AnxA2 activity and bacterial ClfB expression, leading to a significant reduction in the infection levels of S. aureus in MAC-T cells." (PMID 38414081, 2024). "In the case of parasites, bacteria, mycoplasma, fungi, and other pathogens, Annexin A2 binds to the ligand on the pathogen, which mediates the pathogen’s adhesion to the host cell, ultimately leading to infection and damage to the host." (PMID 37482693, 2023). "In line with it, PRV-ΔUS3 infection substantially decreased the ANXA2 extracellular translocation comparing with PRV wild-type strain." (PMID 36786600, 2023). "LppA interacts with multiple ECM components, host plasminogen, and ANXA2, promoting M. bovis colonization and spread during infection." (PMID 37978536, 2023). "Previous studies found that ANXA2 played an anti-inflammatory role in response to an injury or an infection." (PMID 36713082, 2023). "During the adsorption phase of HIV, PS on the virus’s outer envelope binds directly to Annexin A2, facilitating its infection of monocyte-derived macrophages (MDMs)." (PMID 37482693, 2023). "Annexin A2 is a host protein that is helpful to the replication and infection of some viruses, such as measles virus (MV), enterovirus 71 (EV71), and encephalomyocarditis virus (EMCV), by interacting with viral proteins." (PMID 37482693, 2023). "It has been found that Annexin A2 plays an auxiliary role in both the infection and extinction of different parasites." (PMID 37482693, 2023). "To determine the further role of ANXA2 in the infection process, we next performed an RNA-seq analysis for M. bovis infected- siANXA2 transfected EBL cells." (PMID 36159852, 2022). "The colocalization of AnxA2 and HBV was observed at either early or later stages of infection, indicating that AnxA2 is involved in the process of HBV exocytosis." (PMID 34645932, 2022). "The mRNA level of ANXA2 gene increased gradually with infection time, and the difference between 4 and 24 hpi became significant (p < 0.05)." (PMID 36159852, 2022). "Further work is required to ascertain the precise role of AnxA2 during infection and the impact of AnxA2 binding to SopD2 and PipB2." (PMID 34880286, 2021). "A plasma membrane-associated receptor AnxA2 also interacts with enterovirus type 71 (EV71) VP1 to promote virus attachment and infection." (PMID 34681689, 2021). "Autophagy can also serve as a defence mechanisms against bacterial infection, and was de-regulated in a mouse infection model using Anxa2−/− animals." (PMID 33810523, 2021).
infection (continued). "On the other hand, upon infection with Anaplasma phagocytophilum, a Rickettsial organism, annexin AnxA2 null macrophages showed evidence of impaired inflammasome activation." (PMID 32575495, 2020). "In this infection, Anxa2-/- bone-marrow-derived macrophages were less efficient than control macrophages at phagocytosing yeast cells, resulting in a lower frequency of non-lytic exocytosis." (PMID 32575495, 2020). "This appeared to correlate with an inability to clear the infection when annexin A2 is silenced and with the role of AnxA2 in regulating autophagosome formation through the Akt1–mTOR–ULK1/2 signaling pathway." (PMID 32575495, 2020). "Numerous studies demonstrate that AnxA2 is required for optimal endosomal membrane stabilization and autophagosome biogenesis and promotes membrane repair during inflammation and infection." (PMID 32575495, 2020). "The MTT assay showed obviously less proliferation in ANXA2 knock-down group at 4 and 5 d after infection than other groups." (PMID 31186633, 2019). "Stukes and coworkers also tested the significance of annexin A2 during infection, by infecting wild-type and annexin A2 knockout mice with C. neoformans." (PMID 31874916, 2019). "Multiple reports implicating AnxA2 in virus attachment and penetration base their conclusions on experiments that combine studying AnxA2-virus–membrane interactions with infection readouts post-AnxA2 manipulation." (PMID 30568638, 2018). "The data show that upon AnxA2 re-expression and A2t re-stabilization, infection was restored to WT levels, confirming that reduction in HPV16 infection in the A2t KO cells was not due to off-target effects." (PMID 30076379, 2018). "In order to analyze infection rescue in the mCherry-AnxA2-transfected cells, the labeled population was gated on mCherry and analyzed for %GFP-positive cells." (PMID 30076379, 2018). "Upon interaction with host cells, HPV establishes infection by traversing through an endocytic pathway that is clathrin- and caveolin-independent, but dependent on the annexin A2/S100A10 heterotetramer (A2t)." (PMID 30076379, 2018). "After the infection of EGFP‐annexin A2 stable transformant cells with DiI‐labeled U. parvum for 24 hr, annexin A2 signals colocalized with U. parvum." (PMID 28088841, 2017). "We also found that the expression of ANXA2 is slightly increased after infection, especially at late stage." (PMID 28893180, 2017). "The results showed a significant reduction in the progeny viral titer in the supernatant of the ANXA2-knockdown cells at 24 h post infection (pi)." (PMID 28893180, 2017). "Overexpression of ANXA2 resulted in a significant increase in the titer of progeny viruses compared with the empty vector and control group after 12 and 24 h of infection." (PMID 28893180, 2017). "Our results confirm that an interaction occurs between NS1 and ANXA2 after infection of A549 cells with the H5N1 AIV strain." (PMID 28893180, 2017). "This study reveals AnxA2 as a critical regulator in infection-initiated inflammation, which protects the host from excessive inflammatory damage." (PMID 26527544, 2015). "Seven days post-infection, the liver was dissected and AnxA2-HA overexpression was confirmed by Western blotting and immunocytochemistry using anti-HA-HRP and anti-HA antibodies, respectively." (PMID 22848640, 2012). "Pseudo-infection of HaCaT cells was significantly reduced at the concentrations of anti-annexin A2 Ab tested compared to PsV only, though some reduction in pseudo-infection was also observed in the isotype control groups." (PMID 22927980, 2012). "In this study, the abundance of ANXA2 showed weaker increase at early stages of infection with the highly virulent IBV ck/CH/LDL/97I P5 strain than with the attenuated P115 strain." (PMID 22463732, 2012). "A significant reduction in pseudo-infection was observed in the anti-ANXA2 shRNA group that was treated with doxycycline compared to its non-doxycycline control group." (PMID 22927980, 2012).